RAB23 (RAB23, member RAS oncogene family)
Diseases named in the same sentence as RAB23 in open-access papers (continued):
Sharing a sentence is not in itself a finding about the gene and the disease.
gastric cancer (7 papers, 2014 to 2023). A primary or metastatic malignant neoplasm involving the stomach. "Recently, numerous studies have indicated that RAB23 is upregulated in multiple types of tumors and takes part in the tumorigenesis of liver cancer, gastric cancer, prostate cancer, and bladder cancer, and is closely concerned with tumor progression." (PMID 37935937, 2023). "This characteristic of RAB23 expression in BUC was similar to that in gastric cancer, where RAB23 expression levels have a positive correlation with tumor grading." (PMID 37935937, 2023). "Analysis of relative expression levels indicated that IHH, BOC, and RAB23 were decreased in 48%, 54%, and 42% of gastric cancer tissues while 32%, 30%, and 34% of cases showed IHH, BOC, and RAB23 overexpression, respectively." (PMID 33811245, 2021). "We also investigated the expression level of Shh signaling genes including IHH, BOC, and RAB23 in gastric cancer patients." (PMID 33811245, 2021). "In gastric cancer miR-802 was down regulated and found to act as a tumor suppressor by directly targeting RAB23." (PMID 30475821, 2018). "Moreover, our results indicated that RAB23 was downregulated in 42% of gastric cancer tissues while it was overexpressed in 34%of cases." (PMID 33811245, 2021). "The expression of IHH, BOC, RAB23, miR-195-5p, and miR-6738-3p decreased significantly with more advanced cancer stage, and miR-509-3-5p expression was significantly decreased during early stages in gastric cancer patients (P < 0.05)." (PMID 33811245, 2021). "Similarly, BOC and RAB23 and their regulatory miRNAs (miR-6738-3p and miR-509-3-5p) showed opposite expression in 56% and 50% of gastric cancer patients, respectively." (PMID 33811245, 2021). "But in HCC, lung cancer, and gastric cancers, Rab23 was found high expression." (PMID 26716504, 2016). "Rab23 is reported to be overexpressed in gastric cancer and function importantly in tumor invasion." (PMID 25580113, 2014). "In gastric cancers, researchers identified Rab23 as an invasion mediator gene in diffuse-type gastric cancer by using integrative genomics and further demonstrated that overexpression of Rab23 can enhance cell invasion of gastric cancer cells through cell invasion assay in vitro." (PMID 26716504, 2016). "It was reported that miRNA-338-3p could directly target PREX2a, MACC1, Rab14, RAB23, IRS2, and Sox4 in ovarian cancer, gastric cancer, breast tumor, prostate cancer, non-small cell lung cancer, glioblastoma, and neuroblastoma." (PMID 33817311, 2021).
breast carcinoma (6 papers, 2014 to 2024). "In breast cancer cells, activated Rab23 suppresses cell growth and represses DNA synthesis but induces cell apoptosis." (PMID 38695990, 2024). "Overexpression of miR-200b or knockdown of Rab21, Rab23, Rab18, and Rab3B inhibits breast cancer cell proliferation and invasion in vitro." (PMID 28104793, 2017). "In addition, overexpression of RAB23 inhibits breast cancer cells viability and proliferation, and induces cell apoptosis." (PMID 33811245, 2021). "The expressions of RAB21, RAB23, RAB18 and RAB3B were suppressed by transfection of miR-200b in breast cancer cells." (PMID 24447584, 2014). "Over-expression of miR-200b or knock-down of RAB21, RAB23, RAB18 and RAB3B inhibited breast cancer cell proliferation and invasion in vitro." (PMID 24447584, 2014). "Transfection of siRNAs for RAB21, RAB23, RAB18 and RAB3B also inhibits breast cancer cell proliferation and invasion." (PMID 24447584, 2014). "In our study, we identified RAB21, RAB23, RAB18 and RAB3B as novel direct targets of miR-200b in breast cancers." (PMID 24447584, 2014). "The regulations of RAB21, RAB23, RAB18 and RAB3B by miR-200b were further confirmed in breast cancer cell lines." (PMID 24447584, 2014). "Members of RAB family, RAB21, RAB23, RAB18 and RAB3B were novel targets regulated by miR-200b in breast cancer, which could be of promising therapeutic significance." (PMID 24447584, 2014). "Therefore, our results indicated that ectopic expression of Rab23 inhibits the growth and proliferation independent of breast cancer’s estrogen receptor, as well as induces cell apoptosis in breast cancer cells." (PMID 28104793, 2017).
prostate carcinoma (6 papers, 2020 to 2024). A carcinoma that arises from epithelial cells of the prostate gland. "When the expression of miR-338-3p is inhibited, the expression of RAB23 protein will be activated, thus promoting the cell proliferation and metastasis of prostate cancer cells." (PMID 38605206, 2024). "It has been reported that miR-338-3p is down-regulated and targets RAB23 in prostate cancer and the Rab subfamily is a key regulator of cell membrane traffic." (PMID 38605206, 2024). "RAB23 might regulate the proliferation, invasion, and migration of tumor cells, which have been suggested as a potential therapeutic target for prostate cancer treatment." (PMID 37935937, 2023). "In prostate cancer, miR-338-3p inhibits tumor cells tumorigenicity by inactivating RAB23." (PMID 34718336, 2021).
sarcoidosis (5 papers, 2012 to 2023). Sarcoidosis is a multisystemic disorder of unknown cause characterized by the formation of immune granulomas in involved organs. "An interesting association has been shown in a German study between the RAB23 gene on chromosome 6p21 and sarcoidosis, focusing on a non-synonymous SNP variant, rs10484410 (G207S)." (PMID 32823753, 2020). "RAB23 polymorphisms have been further linked to an increased risk of sarcoidosis-associated uveitis." (PMID 32823753, 2020). "In addition to the implication of dysregulated Rac1-related pathways, genetic variants of some Rab proteins, such as Rab23, correlate with some phenotypes of sarcoidosis." (PMID 34440765, 2021). "The identified association of the 6p12.1 locus with sarcoidosis further implicates this locus may be a crossing susceptibility factor and Rab23 may play a potential role in the pathophysiology of sarcoidosis." (PMID 28104793, 2017). "We replicated associations for several previously reported sarcoidosis susceptibility risk loci in our AA collection including MHC Class II region genes (HLA-DRA, HLA-DRB5, HLA-DRB1, and HLA-DQA1), BTNL2, RAB23, and ANXA11." (PMID 22952805, 2012).
squamous cell carcinoma (4 papers, 2016 to 2023). A carcinoma arising from squamous epithelial cells. "The results indicated that Rab23 promotes squamous cell carcinoma cells migration and invasion requires activation of Rac1." (PMID 26716504, 2016). "Taken together, our results indicated that Rab23 promotes squamous cell carcinoma cells migration and invasion by regulating Integrin β1/Tiam1/Rac1 pathway." (PMID 26716504, 2016). "The results indicated that Rac1 activation was involved in Rab23 promoted squamous cell carcinoma cells migration and invasion." (PMID 26716504, 2016). "Interestingly, Rab23 was found to be over-expressed in squamous cell carcinoma cells, and it was demonstrated that active Rab23 interacts with β1 integrin and, through it, with Tiam1, which mediates Rac1 activation and cell migration and invasion." (PMID 31035701, 2019).
bladder cancer (3 papers, 2012 to 2023). "Meanwhile, we explored the role of miR-367-3p and RAB23 in the treatment of bladder cancer with cisplatin by CCK-8 assay." (PMID 37935937, 2023). "The immunohistochemical data indicated there was much more RAB23 protein in the bladder cancer samples relative to that in normal bladder urothelial samples." (PMID 37935937, 2023). "Results also indicated overexpression of miR-367-3p inhibited the tumorigenesis of bladder cancer by repressing RAB23 expression." (PMID 37935937, 2023). "We then performed an EdU assay to verify the effect of RAB23 on the proliferation of bladder cancer cells after cisplatin treatment." (PMID 37935937, 2023). "The results showed that β-galactosidase activity was significantly reduced and cellular DNA MMR activity was increased in bladder cancer cells with knockdown of RAB23 compared with the control group." (PMID 37935937, 2023). "Meanwhile, our results showed that down-regulation of RAB23 increased the sensitivity of bladder cancer cells to cisplatin and decreased cell survival." (PMID 37935937, 2023). "A previous study has demonstrated that RAB23 overexpression can promote proliferation and invasion of bladder cancer cells." (PMID 37935937, 2023). "This is consistent with the results of in vitro experiments, indicating that knockdown of RAB23 enhances cisplatin sensitivity in bladder cancer." (PMID 37935937, 2023). "This study sought to elucidate the potential regulatory mechanism of miRNAs, namely, miR-367-3p, on RAB23 gene expression and the effect of miR-367-3p on cisplatin sensitivity in bladder cancer cells." (PMID 37935937, 2023). "This study investigated the biological role of miR-367-3p upregulation in bladder cancer and verified the mutual relation between miR-367-3p and RAB23." (PMID 37935937, 2023). "A dual luciferase reporter assay was used to confirm whether miR-367-3p binds to the 3′ UTR of RAB23 mRNA and affects the tumorigenic activity of bladder cancer cells." (PMID 37935937, 2023). "miR-367-3p acts as a tumor suppressor in bladder cancer by downregulating RAB23 signaling." (PMID 37935937, 2023). "As suggested, miR-367-3p in bladder cancer cell lines directly targets RAB23 mRNA." (PMID 37935937, 2023). "miR-367-3p overexpression enhances the sensitivity of bladder cancer cells to cisplatin, for which RAB23 may be a target." (PMID 37935937, 2023). "We conjecture that miR-367-3p-mediated downregulation of RAB23 expression may be a new therapeutic strategy for bladder cancer." (PMID 37935937, 2023). "We conjecture that miR-367-3p-mediated downregulation of RAB23 expression may be a new therapeutic strategy for bladder cancer treatment." (PMID 37935937, 2023). "A dual-luciferase reporter gene assay was then conducted to determine whether miR-367-3p directly suppresses the RAB23 expression in bladder cancer cells by the construction of luciferase reporter vectors containing wt or mut sequences of RAB23 3′ UTR." (PMID 37935937, 2023). "In addition, upregulated RAB23 expression is observed in bladder cancer specimens and malignant cell growth and invasion capacity get enhanced via the NF-κB pathway." (PMID 37935937, 2023). "RAB23 was shown to be upregulated in bladder cancer tissues and cell lines." (PMID 37935937, 2023). "Obviously, a negative correlation between miR-367-3p and RAB23 expression levels exists in bladder cancer samples." (PMID 37935937, 2023). "Second, significantly altered miRNAs in recurrent bladder cancer were identified, with miR-154-5p showing the highest level of editing in recurrent bladder cancer and may up-regulate the expression levels of downstream targets HS3ST3A1, AQP9, MYLK, and RAB23." (PMID 36199571, 2022). "However, the biological functions of RAB23 in human bladder cancers had not been clearly defined." (PMID 37935937, 2023). "However, whether miR-367-3p can regulate the RAB23 expression and impact the proliferation, invasion, and migration of bladder cancer cells has not yet been elucidated." (PMID 37935937, 2023).
ciliopathy (3 papers, 2021 to 2025). A genetic disorder of the cellular cilia or the cilia anchoring structures, the basal bodies, or of ciliary function. "Collectively, these results further suggest that the loss of RAB23 function causes a ciliopathy in humans." (PMID 40825043, 2025). "Despite these clinical similarities and recent speculations on the association between RAB23 and ciliopathy, it remains unclear whether patients with CS exhibit defective primary cilia." (PMID 40825043, 2025). "This strongly suggests that the loss of Rab23 function leads to ciliopathy in the mouse mutants." (PMID 40825043, 2025). "Importantly, our collective results show that different vertebrate models of RAB23 loss-of-function mutants consistently presented with several pathological phenotypes and cellular characteristics typical of human ciliopathies." (PMID 40825043, 2025). "Although the clinical features of CS bear some resemblance to those of ciliopathies, the exact relationship between the pathological manifestations of CS and the ciliary function of RAB23 remains ambiguous." (PMID 40825043, 2025). "Considering the important roles of Rab23 in ciliary trafficking, earlier studies have speculated on the potential connection between Rab23 and ciliopathy." (PMID 40825043, 2025). "The Rab23-CKO mutants exhibit multiple developmental and phenotypical traits recapitulating the clinical features of human ciliopathies and CS, indicating a causal link between the loss of Rab23 and ciliopathy." (PMID 40825043, 2025). "Considering the apparent phenotypic correlation with ciliopathies, we investigate whether the deletion of Rab23 would disrupt primary cilium formation and/or affect its structural integrity." (PMID 40825043, 2025). "We identified 10 genes (STK38L, TUBB2A/B, CCNO, ARL13B, RFX2, RAB23, TUBA1C, CEP170B, and SPATA7) that are established or candidate ciliopathy genes." (PMID 34485842, 2021).
liver cancer (3 papers, 2014 to 2024). An epithelial or non-epithelial malignant neoplasm that arises from the liver. "Sicklick's study revealed Rab23 had elevated levels in human liver cancer tissues or liver cancer cells and was closely associated with tumor size." (PMID 37884351, 2024). "This suggests that Rab23 plays an essential role in liver cancer development and the SHH signaling pathway, which is consistent with our previous studies." (PMID 37884351, 2024). "Immunohistochemical (IHC) staining showed reduced Rab23 expression in knockout liver cancer cells, along with decreased levels of KI‐67, a proliferation marker for human tumors that has been strongly linked to advanced HCC." (PMID 37884351, 2024). "Disrupting this binding or reducing the level of Rab23 has a significant impact on the expression and nuclear localization of Gli1 in human liver cancer cell line Hep3B and HepG2, ultimately leading to suppression of cell growth." (PMID 37884351, 2024). "Another RAB family member, RAB23 has been identified as an antagonist of Sonic Hedgehog signaling pathway which is deregulated in many cancers, and found to over-expressed in gastric and liver cancer." (PMID 24447584, 2014). "Currently, only a limited number of papers have reported on the role of Rab23 in HCC, and the specific molecular mechanisms by which Rab23 promotes the progression of liver cancer are far from being elucidated." (PMID 37884351, 2024).
osteosarcoma (3 papers, 2020 to 2025). A usually aggressive malignant bone-forming mesenchymal neoplasm, predominantly affecting adolescents and young adults. "Similar to RAB23 deficient mouse calvaria derived primary cells, we demonstrate reduced transferrin uptake in human osteosarcoma cells (MG-63) where the expression of RAB23 was reduced by siRNA-mediated knockdown." (PMID 40261407, 2025). "We normalized transferrin uptake in RAB23 knockdown human osteosarcoma cells (MG-63) by overexpressing RAB23." (PMID 40261407, 2025). "RAB23 was over-expressed in human osteosarcoma MG-63 cells by using N-terminally HA-tagged full-length RAB23, HA-RAB23 pcDNA3.1 expression vector." (PMID 40261407, 2025). "We demonstrate that knockdown of RAB23 in human osteosarcoma cells (MG-63) also reduces transferrin uptake, and that this can be normalized by overexpressing of RAB23." (PMID 40261407, 2025). "In osteosarcoma, miR-665 regulates Rab23 expression to inhibit tumor invasion and metastasis." (PMID 34497766, 2021).
congenital heart disease (2 papers, 2024). A heart disease that is present at birth. "Since the original description of RAB23-associated CRPTS in 17 affected individuals, a further 22 cases have been described with common additional features including facial dysmorphism, short stature with obesity, cryptorchidism, congenital heart disease and variable developmental delay." (PMID 38760421, 2024).
cryptorchidism (2 papers, 2018 to 2024). The failure of one or both testes of a male fetus to descend from the abdomen into the scrotum during the late part of pregnancy. "Combined with previously reported males with MEGF8-associated CRPT2, all males with MEGF8-associated CRPTS have demonstrated cryptorchidism, which is also common but not universally reported in RAB23-associated CRPT1 (MEGF8: 9/9 males; RAB23 14/23 males; Fisher’s exact P = 0.035)." (PMID 38760421, 2024).
lung carcinoma (2 papers, 2016 to 2017). "Unlike in HCC and lung cancer, the localization of Rab23 in other cancer tissue or cell lines is cytoplasmic positivity." (PMID 28104793, 2017). "In many lung cancer specimens, Rab23 was found localized in the nuclei, but no Rab23 expression was detected in normal lung tissue." (PMID 26716504, 2016).
ovarian carcinoma (2 papers, 2021 to 2023). A malignant neoplasm originating from the surface ovarian epithelium. "Recent studies have revealed that RAB23 is involved in several biological processes in malignant tumors, and a related study found that RAB23 has a significant function in the progression of cisplatin resistance in ovarian cancer." (PMID 37935937, 2023).
papillary thyroid carcinoma (2 papers, 2016 to 2017). "Down-regulation of Rab23 was seen in three thyroid malignant cohorts; follicular thyroid carcinoma, papillary thyroid carcinoma and follicular variant of papillary thyroid carcinoma when compared with the benign follicular adenoma group." (PMID 26716504, 2016).
basal cell carcinoma (1 paper, 2016). A carcinoma involving the basal cells. "As SHH signaling has been shown to be tumorigenic in various cancer types such as small cell lung cancer, colorectal adenocarcinoma, basal cell carcinoma, and even SCC itself, Rab23 was recognized as a negative regulator of carcinoma." (PMID 26716504, 2016).
colorectal cancer (1 paper, 2020). A primary or metastatic malignant neoplasm that affects the colon or rectum. "In addition, miR-84 suppressed cell proliferation, migration, and metastasis in renal cell carcinoma and colorectal cancer by targeting and interacting with RAB23 and KRAS/CDC42 axis, respectively." (PMID 33817254, 2020).
cutaneous squamous cell carcinoma (1 paper, 2016). "However, the function and regulatory mechanism of Rab23 in cutaneous squamous cell carcinoma was unknown." (PMID 26716504, 2016).
esophageal cancer (1 paper, 2018). A primary or metastatic malignant neoplasm involving the esophagus. "miR-92b-3p has been reported to play a tumor-suppressing role in esophageal cancer by silencing RAB23 or integrin α6." (PMID 29661250, 2018).